CD34 (CD34 molecule)
Diseases named in the same sentence as CD34 in open-access papers (continued):
Sharing a sentence is not in itself a finding about the gene and the disease.
tumor (continued). "HF stem cell markers such as Nuclear factor of activated T-cells, cytoplasmic 1 (NFATc1), CD34 and Prominin-1/CD133 are all known to contribute in regulating epidermal stem cell quiescence, location, proliferation, wound healing and in tumor formation." (PMID 22383956, 2012). "Consistent with the results of in vitro experiments, EP decreased U266 tumor growth as well as suppressed the expression levels of phospho-STAT3 and CD34 by immunohistochemistry." (PMID 22260501, 2012). "Immunohistochemically, the tumor cells expressed usual vascular antigens CD31 and CD34 as well as mesenchymal marker, Vimentin." (PMID 22280556, 2012). "In the tumor-host interface of DCIS-MI, stromal fibroblasts exhibited SMA-CD34+FAP-α-, however, in the tumor-host interface at the invasive front of DCIS-MI lesions, stromal fibroblasts exhibited mainly immunophenotype of SMA+CD34-FAP-α+." (PMID 22067528, 2011). "Immunohistochemically, the tumor cells are diffusely positive for vimentin and focally for CD68 and CD34." (PMID 22567356, 2011). "Cancer patients were treated twice with autologous CD34+ hematopoietic stem cell-derived, GM-CSF/IFN-γ-differentiated DCs pulsed with autologous tumor lysate and KLH, by 4-week interval." (PMID 22013914, 2011). "In general, the MVD has been quantified by immunohistochemical staining of tumor blood vessels with the use of antibodies, including CD31, CD34, von Willebrand Factor (vWF) or Factor VIII-related antigen (FVIII) and CD105." (PMID 24212960, 2011). "In the tumor-host interface of DCIS and IDC, stromal fibroblasts exhibited mainly immunophenotype of SMA+CD34-FAP-α+." (PMID 22067528, 2011). "Immunohistochemistry revealed the tumor cells to be strongly and diffusely positive for CD31 and CD34 with focal reactivity for pancytokeratin." (PMID 20165548, 2010). "It has also been reported that high CD34+ MVD and tumour vessel invasion are more closely related to poor survival than the other neoangiogenetic factors in stage IB-IIA NSCLC." (PMID 19216806, 2009). "Umbilical cord blood (UCB) is increasingly used as an alternative source of transplantable CD34+ haematopoietic stem cells (HSC) for neoplastic and non-neoplastic diseases." (PMID 19712464, 2009). "The transcripts of murine CD31, CD34, CD45 and VWF were also detected in some tumors with variable levels, suggesting that host endothelial progenitors were involved in tumor angiogenesis to some extent." (PMID 18286204, 2008). "In all specimens, CD34 and CD31 similarly highlighted spindled tumor cells and the abnormal vasculature within these lesions." (PMID 18651955, 2008). "After the tumour cell lines, the vectors were tested – as a proof-of-principle – on primary human CML and primary CD34+ PBPC." (PMID 18789140, 2008). "Immunohistochemical studies on that tumor cells revealed positive staining for C-KIT (CD117), whereas CD34, antibodies against smooth-muscle actin (SMA), desmin, actine and S-100 protein were negative." (PMID 17958889, 2007). "Immunohistochemically the tumor cells are positive for Von-Willebrand factor, CD31, CD34 and vascular endothelial growth factor receptor-3 (VEGFR-3)." (PMID 16859564, 2006). "Immunofluorescence colabeling of PRL-3 and the vascular endothelial marker CD34 was performed to proof expression of PRL-3 not only in breast cancer tumour cells, but also in tumour vasculature." (PMID 16832410, 2006). "Tumor vasculature (as measured by microvessel determination using antibodies to endothelial markers such as CD31, CD34, CD105) is strongly related throughout a tumor section (p < 0.01)." (PMID 15743520, 2005). "To investigate the association between Id-1 expression and cell proliferation or tumour angiogenesis, we examined PI, AI and MVD in tumour cells using Ki-67, TUNNEL and CD34 staining, respectively." (PMID 15026801, 2004).
tumor (continued). "In vitro, it has been demonstrated that factors that can be produced by tumour cells, including vascular endothelial growth factor (VEGF), M-CSF and IL-6, inhibit DC maturation from CD34+ cells." (PMID 14562018, 2003). "NAC-HCPS significantly reduced the number of CD34 positive vessels (P=0.0031), suggesting that NAC-HCPS significantly inhibited angiogenesis in tumours." (PMID 12087470, 2002). "General finding in all examined types of BCCs was the absence of CD34 positivity in neoplastic cells, and in extravascular structures of papillary dermis and tumor stroma." (PMID 41597444, 2026). "A frequent accompaniment of superficial BCCs was a moderately expressed CD34-negative lymphocytic–plasmacytic infiltrate of the surrounding tumor stroma." (PMID 41597444, 2026). "The tumor stroma was CD34 immunopositive in six out of twenty examined cases in this group (6/20), while in the rest of examined samples the extravascular CD34 immunopositivity was absent." (PMID 41597444, 2026). "Tumor cells were negative for CD34, TFE3, STAT6, ALK1, PAX8, AE1/3, and other epithelial, neural, and myogenic markers." (PMID 40948436, 2026). "Our results suggest that the juxtatumoral zone shows a more pronounced structural organization and very strong CD34 immunopositivity in superficial and solid/cystic BCC, where this zone completely encircles the tumor mass and separates it from adjacent reticular dermis." (PMID 41597444, 2026). "These PAS‐positive and CD34‐negative patterns were found in the viable areas of the tumor, where they formed different morphological patterns." (PMID 40832718, 2026). "The infiltrative type of BCC exhibited a markedly more prominent tumor stroma, whose perinodular and internodular compartments showed a monomorphic pattern of absence of extravascular CD34 immunoreactivity in the examined cases." (PMID 41597444, 2026). "In principle, the extravascular part of tumor stroma in all analyzed BCC types was not labeled with CD34." (PMID 41597444, 2026). "The extravascular CD34 immunopositivity was absent in papillary dermis in the tumor region, as well as in the peritumoral and marginal skin in all examined types of BCC." (PMID 41597444, 2026). "In our case, the tumor cells were positive for CD34 and CD99 while negative for smooth muscle Actin, Desmin and S100." (PMID 40709355, 2025). "Therefore, immunohistochemistry (IHC) is necessary to confirm the tumor’s endothelial origin, with markers like CD31, CD34, FLI1, and ERG being particularly useful for identifying vascular differentiation." (PMID 40004808, 2025). "Specifically, if a tissue sample shows PAS-positive staining but is negative for both CD31 and CD34, it indicates that these structures are composed of tumor cells rather than endothelial cells, thereby supporting the presence of VM." (PMID 41019994, 2025). "Double staining for integrin β6 and CD34 confirmed that integrin β6 was expressed on the membrane of cancer cells but not in the neovascular endothelium within the tumor stroma." (PMID 40899568, 2025). "Immunohistochemical stain showed that tumor cells co-expressed actin, desmin, and caldesmon, whereas S100 protein, CD34, and DOG-1 were negative." (PMID 40951205, 2025). "This elevated metabolic activity may be attributed to the tumor’s angiogenic properties, such as high expression of CD31 and CD34, explaining the observed hypermetabolic phenomenon." (PMID 41255623, 2025). "TAMs can support the survival of CD34-negative tumor-initiating cells and promote melanoma progression." (PMID 40399946, 2025). "Surprisingly, the numbers of both lymphatic (LYVE-1) and vascular (CD34) vessel counts significantly increased after PRRT treatment, suggesting the activation of a compensatory mechanism that may support tumor survival." (PMID 41012550, 2025). "In this way, CD34 was differential between the two tumor types but not in a previously reported pattern." (PMID 39804140, 2025).
tumor (continued). "The paediatric case carried an IGL::MYC translocation and was TdT‐positive in 40% of the tumour cells but CD34‐negative." (PMID 41047873, 2025). "On IHC, tumour cells were positive for Vimentin, CD34 and S-100, while negative for STAT6, SMA and CK." (PMID 40556788, 2025). "Tumor cells express diffuse positive expression for smooth muscle actin and β-catenin, while negative reaction for CD34 and STAT6." (PMID 41226013, 2025). "Additionally, tumor cells often exhibit immunoreactivity for endothelial markers such as ERG, CD31, CD34, and factor VIII-related antigen." (PMID 40895865, 2025). "Some IS tumor cells expressed MDM2 (8/11, 72.7%), SMA (3/11, 27.3%), and CD34 (2/11,18.2%)." (PMID 41246336, 2025). "In another mGT case, Pabuççuoğlu and Lebe observed CD34 and MMP-9 expression, suggesting that MMP-9, produced by both tumor cells and mast cells, may contribute to the development of the myxoid stroma through extracellular matrix remodeling." (PMID 41300877, 2025). "Thus, 25% of CD34-positive patients (n = 6) and 64.44% of CD4-negative patients (n = 29) had tumor margin infiltration." (PMID 40362599, 2025). "Immunohistochemical stains showed that the tumor cells expressed α-smooth muscle actin, desmin, and caldesmon, whereas S100 protein, CD34, and DOG-1 were negative." (PMID 40951205, 2025). "The tumour does not exhibit a plexiform growth pattern; immunohistochemical studies have detected the expression of CD34 but not of SMA." (PMID 41357577, 2025). "However, angiosarcoma tumor cells invariably show immunoreactivity for one or more endothelial markers (factor VIII, CD31, CD34), as well as epithelial markers such as cytokeratins and concomitant negativity for thyroglobulin or podoplanin (D240)." (PMID 40214777, 2025). "Positive staining of PD-L1, CD31 (partial +), CD34, CD68, CD163, vimentin and SMA detected in the tumor tissue, indicating that vascular endothelial cells, TAMs and fibroblasts may participate in the pathogenesis of ENKTL." (PMID 40433378, 2025). "In this case, spindle and stellate tumor cells were strongly positive for vimentin and CD34, and negative for CK, desmin, SMA, HMB-45, MDM2, CDK4, p16, β-catenin, and STAT6." (PMID 41458523, 2025). "Immunohistochemical studies revealed that the tumor cells tested positive for beta-catenin, with nuclear staining, and negative for CD34, CD117, desmin, and S100." (PMID 39278889, 2025). "PMT tumor cells generally lacked immunoreactivity for endothelial markers such as CD34 and CD31 when these markers were included in immunohistochemical examinations." (PMID 41182108, 2025). "Accordingly, we observed that the median percentage of CD34+/CD45dim/CD117+ cells negative for annexin V at baseline was significantly lower in patients with tumor response, as compared to those with stable or progressive disease (p = 0.005)." (PMID 39941866, 2025). "Most tumor cells are spindle-shaped, and the immunophenotype is positive for SMA, Desmin, and CD34." (PMID 41137250, 2025). "Immunohistochemical analysis demonstrated positive expression of CK, vimentin, and CD34 in tumor cells, with negative immunoreactivity for INSM1, S100, and CD68—findings consistent with the established pathological diagnostic criteria for ES." (PMID 41244767, 2025). "Tumours with an immature granulocytic profile express CD34 and KIT (CD117), whereas CD34 is negative in tumours with a more mature profile." (PMID 39996833, 2025). "Another notable aspect of our study was the use of a reliable preclinical organoid model of EGC combined with scRNA‐seq data and the finding that IL‐33+ endothelial cells can promote angiogenesis and tumor proliferation in EGC by influencing adhesion molecules (PECAM1, CD34, and KRT17)." (PMID 40860436, 2025). "The first-line markers for diagnosing these tumors are bcl-2 and CD34; a tumor that tests negative for both markers is unlikely to be SFT." (PMID 40709355, 2025).
tumor (continued). "Pathology confirmed that the tumor was composed primarily of round epithelioid cells, immunohistochemically positive for CD34 and negative for C-kit." (PMID 40507589, 2025). "In contrast,EC5 and EC6 subclasses exhibited conserved pro-angiogenic signatures encompassing established vascular morphogenesis regulators (CD34,AQP1) and emerging angiocrine signaling components (RAMP2/3,CRIP2,PCDH17),consistent with previous reports on tumor neovascularization dynamics." (PMID 41394809, 2025). "The three adult cases lacked MYC translocation; two showed diffuse positivity for both TdT and CD34, and the remaining case was TdT‐positive in ~80% of tumour cells but lacked any CD34 expression." (PMID 41047873, 2025). "Tumor margin infiltration was observed less frequently in CD34-positive patients, being more common in CD34-negative cases." (PMID 40362599, 2025). "Immunophenotyping found tumor cells that were CK (+), CD56 (+), Syn (+), EMA (+), β-catenin (membrane +), LCA (−), CD99 (−), S100 (−), HMB-45 (−), SOX-10 (−), TTF-1 (−), CDX-2 (−), and CD34 (−), along with a Ki-67 proliferation index of 60–70%." (PMID 41245381, 2025). "The immunohistochemical examination showed that the tumor cells were positive for CD34 and CD99 while negative for smooth muscle Actin, Desmin, and S100." (PMID 40709355, 2025). "CD34 (clone QBEnd/10) staining highlighted numerous small vessels but was mostly negative in tumor cells." (PMID 41230282, 2025). "Even though specific immunohistochemical markers for DFSP are lacking, the tumour cells typically demonstrate positivity for CD34 and vimentin on immunohistochemistry analysis." (PMID 40556795, 2025). "Immunohistochemically, the tumor cells were positive for CD34 and negative for smooth muscle actin, desmin, SOX10, S100, EMA, MUC4, and STAT6." (PMID 40677885, 2025). "Histopathological examination of the epididymal biopsy showed tumor cells with specific morphological features, and immunohistochemistry (IHC) indicated CD31(+), CD34(+), Fli-1(+), ERG(+), Ki-67(+5%+), along with WWTR1-CAMTA1 gene fusion by fluorescence in situ hybridization (FISH), confirming EHE." (PMID 40978723, 2025). "If more than 1% of tumor cells exhibit membrane staining, the tumor is considered PD-L1-positive.Meanwhile, the tumor tested negative for CD34, EMA, ERG, S100, HMB45." (PMID 41293148, 2025). "Therefore, the collective data suggest CD34+CLDN5+ ECs promoted the development of CCA and recruited MSCs into TME, with these ECs exhibiting elevated expression of IGF2 within the tumor." (PMID 39674501, 2025). "These statistical tests indicated that CD34-positive patients had a moderate tendency to present tumor margin infiltration less often or not to present tumor margin infiltration." (PMID 40362599, 2025). "While CD34 positivity in tumor cells is commonly reported in PSS, its absence does not exclude the diagnosis, as CD34 expression on tumor cells can be variable." (PMID 40686513, 2025). "Recent exploration of the relationship between the expression of CD34 and other molecular markers in HCC revealed an inverse correlation between the expression of CD34 and C-type Lectin Domain Family 4 Member G (CLEC4G) in HCC tumor tissues." (PMID 40941632, 2025). "Repeat immunohistochemical staining revealed tumor cells positive for CD34 and p16, and negative for smooth muscle actin, desmin, S100, and SOX10, except for the lipoblasts, which were positive for S100 and SOX10." (PMID 40677885, 2025). "The expression of CD31 and CD34 was not changed in the PAK1&4KO tumours, indicating that PAK4KO dominated the effect on angiogenesis and compromised PAK1KO-decreased angiogenesis." (PMID 41228228, 2025). "The myofibroblastic nature of the tumor is highlighted by the immunohistochemical positivity of the neoplastic cells for smooth muscle actin (SMA), with varying degrees of desmin, calponin, and CD34 positivity." (PMID 41255404, 2025).
tumor (continued). "Unlike PAK1KD tumours, PAK4KO increased angiogenesis, as evidenced by an enlarged vessel diameter, an increased MVD of large vessels, and elevated CD31 and CD34 expression associated with increased fibronectin deposition within the tumours." (PMID 41294859, 2025). "CRISPR-mediated CXCL10 knock-in enhances CAR T cell infiltration and antitumour efficacy in vitro and in vivo, including humanized CD34+ HuNOG mice, where CXCL10-expressing tumours show stronger immune infiltration and prolonged tumour control within a reconstituted human immune microenvironment." (PMID 41366257, 2025). "There were no signs of tumor growth at the injection sites or in different organs in nude mice injected with transduced human CD34+ cells; however, tumors were identified at these sites in the positive group." (PMID 40092492, 2025). "The tumour cells were positive for Vimentin, CD34 and S-100 positive, while negative for SOX 10, EMA, SMA and Melan A. Ki 67 was approximately 11%." (PMID 40556788, 2025). "Using a CD34+ humanized PDX model representative of a metastatic pS6high uLMS, we demonstrate that pharmacological inhibition of the PI3K/mTOR pathway elicits anti‐tumour immune responses and sensitises these tumours to PD‐1 blockade." (PMID 38711203, 2024). "Immunohistochemically the tumor cells were positive for CD31, CD34 and ERG." (PMID 39287168, 2024). "Immuno-Histochemistry showed CD34 as negative in lining of ureter CAIX as positive in tumor, CD10 as positive in tumor, PAX8 as positive in tumor, CK7 as negative in tumor." (PMID 38952497, 2024). "In the validation cohort, tumor number, size, age, differentiation, MVI, GGT, CD34, CD66b, Treg/CD8, CCR4-T, CCL17-T, CCL17-I, HHLA-2, CD73-T, and CCR4 + CD73 + cells have been proved to be prognostic variables for both OS and RFS in univariate analysis (all P < 0.050)." (PMID 38914802, 2024). "When C48 (CD34+ endothelial cells) acted as the ligand, several chemokine ligands were predicted to interact with chemokine receptors on C21 in both nontumor and tumor regions." (PMID 39761010, 2024). "Finally, to test whether ISB 2001 has any on-target off-tumor activity in vivo, we quantified the number of hematopoietic progenitors, B cell-committed progenitors and mature T cells present in the bone marrow of CD34+ humanized NXG mice 3 days after treatment with ISB 2001 (1.5 mg kg−1)." (PMID 39261676, 2024). "CD8+ T cells, originating from CD34 hematopoietic stem cells located in the bone marrow, can be activated by endogenous antigenic peptides presented in MHC class I molecules, thereby exerting anti-tumor immunity." (PMID 38629071, 2024). "Additionally, CD34, FN1, LOXL2, and VCAN are key players in tumor angiogenesis, invasion, and metastasis." (PMID 39012409, 2024). "Immunohistochemical staining revealed that the tumor was positive for alpha-smooth muscle actin, but negative for CD34, desmin, keratin 18, S-100 protein, melan A, c-kit, and STAT6." (PMID 38805072, 2024). "The tumor cells were negative for HepPar1, glutamine synthetase, arginase 1, glypican 3, S100, CD34 and CD31." (PMID 39021472, 2024). "A biopsy of this emerging tumor revealed the presence of granulation tissue with reactive fibrous changes, and the tumor tested negative for CD34, indicating the absence of tumor metastasis." (PMID 38865945, 2024). "Immunohistochemical analysis demonstrated the positive expression of S100A4, CDK4, MDM2, CD34, and Vimentin, along with the negative expression of Leptin, confirming the tumor’s high aggressiveness and malignancy." (PMID 39591300, 2024). "Among these, the expression of STAT6 in the tumor cell is essential for diagnosis when CD34 and CD99 are negative." (PMID 39574987, 2024). "And IHC of Ki67, CD34 and CD31 showed that overexpression or knockdown of LINC00460 significantly increased or decreased the cell proliferation and angiogenesis in subcutaneous tumor, liver and lung metastases." (PMID 39135122, 2024).